RN7SL113P (RNA, 7SL, cytoplasmic 113, pseudogene)
Gene: Miscellaneous RNA gene on chromosome 2 (85,368,282 to 85,368,580, forward strand). Ensembl gene ENSG00000278590.
Homologues: Orthologues: chimpanzee Metazoa_SRP (99% identical), macaque Metazoa_SRP (94% identical). Paralogues in human: RN7SL1 (86% identical), RN7SL2 (85% identical), RN7SL3 (85% identical), RN7SL559P (82% identical), RN7SL732P (82% identical), RN7SL220P (82% identical), RN7SL566P (82% identical), RN7SL712P (82% identical), RN7SL714P (82% identical), RN7SL828P (82% identical), Metazoa_SRP (81% identical), RN7SL45P (81% identical), and 704 more.